TNF (tumor necrosis factor)
Diseases named in the same sentence as TNF in open-access papers (continued):
Sharing a sentence is not in itself a finding about the gene and the disease.
infection (continued). "A detailed measurement of levels of 23 cytokines in the BAL, at 2-day intervals between days-0 to 25 revealed maximal elevation of inflammatory cytokines IL1a, IL1b, IL6, TNFα, IFNγas well as chemokines mKC, Eotaxin, MIP1a, MIP1b and MCP1 during the days 5–9 of infection (Fig-1A & Fig-S1)." (PMID 24505273, 2014). "The presence of 33 nm AgNPs at infection led to significantly up-regulated TNF-α, IL-10, CCL2 and down-regulated IL-6 production (p≤0.05), while 46 nm AgNPs significantly down-regulated TNF-α and IL-6 (p≤0.05)." (PMID 25117537, 2014). "It should also be noticed that endogenous production of TNF-α by UVB-irradiated keratinocytes was not altered by HPV38 E6/E7 infection." (PMID 23533798, 2013). "The lack of TNF/TNFR2 signaling results in an additional 1000-1500 antigen-specific CD8 T cells on day 12 post-infection compared with mice that received WT cells." (PMID 23874808, 2013). "TNF-α and IL-1β were both upregulated during infection of normal CEACAM1-humanized but not significantly in WT mice." (PMID 23935487, 2013). "Based upon these data, we speculate that the suppression of TLR7/8-mediated TNF-α and IL-6 expression by MSC-conditioned medium modulates the pathogenesis of ssRNA virus infection, including infection by influenza virus." (PMID 24191131, 2013). "At 1 dpi, a statistical difference in the upregulation of interleukin-4 (IL-4), interleukin-6 (IL-6), tumor necrosis factor (TNF), and interferon-γ (IFNγ) was observed between NiV-M and NiV-B infections, with higher expression of these genes in response to NiV-M." (PMID 23342177, 2013). "Interestingly, a more rapid decline of the IFNB1 mRNA level is observed at 48 hours post-infection compared to IFIT1 and TNF mRNA levels, which remained higher at this time point." (PMID 23785285, 2013). "In our study, we used gene knockout mice incapable of TNF-α production, and found that clearance of both primary and secondary infection was not significantly affected in the complete absence of TNF-α production." (PMID 23483844, 2013). "At 2 days after infection, the levels of IL-1, IL-6, TNF-α, and IL-10 were reduced; at 14 days after infection, the levels of IL-1, KC, TNF-α, and IFN-γ were reduced, and a reduction in the IL-6, KC, and IL-10 concentrations was observed at 28 days after infection." (PMID 23818746, 2013). "We observed a significantly decreased percentage of TNF-α- expressing monocytes in HSV-2 infected Fas and FasL-deficient mice at 3 day (p≤0.01), but not at 7 day of infection in comparison to HSV-2 infected wild-type strain." (PMID 23922974, 2013). "Blocking TNF has previously been shown to be effective in limiting vascular leakage at late time points of infection in immunocompromised mice lacking Type I and II Interferon receptors (IFN-α,β,γ-R−/−, or AG129), which is a mouse model of DENV viremia." (PMID 23638300, 2013). "In terms of cytokine secretion, BtpB did not seem to be involved in the control of TNF-α secretion during infection of murine DCs." (PMID 23847770, 2013). "Based on previous studies demonstrating TNFα as a key regulator of LN hypertrophy and cellularity and as mediator of vascular changes, the ability of the LN feed arteriole to remodel during infection in the absence of TNFα was examined." (PMID 23573281, 2013). "In contrast, treatment with these drugs inhibited TNFα secretion with or without infection, and budesonide or combination of budesonide and formoterol inhibited CXCL8 secretion after infection." (PMID 24219422, 2013). "Since TNF induces PTX3 expression, one explanation for reduced production of TNF in this infection model could be a feedback mechanism to regulate PTX3 levels and exacerbations that may result from its very high levels." (PMID 23755050, 2013). "The other 4 cytokines (TNF-α, IL-1α, IL-1β, and eotaxin) were elevated in non-surviving infected mice only at 48 hours after infection." (PMID 23520553, 2013).
infection (continued). "The mRNA level of p62 did not change after TNF-α treatment, although infection has been reported to induce its transcription in some studies." (PMID 23936437, 2013). "Since IL-10 is a pro-inflammatory cytokine produced at the site of inflammation, increased IL-10 expression soon after infection in late infected mice might result in less IFN-γ and TNF-α production thereby reducing cholangiocyte damage." (PMID 23844248, 2013). "Here we show that proinflammatory cytokine TNFα plays a critical role in RB51-induced macrophage cell death, however, TNFα appears not to play an important role in macrophage cell death induced by the infection of strain CA180, another B. abortus rough strain." (PMID 24350060, 2013). "Six weeks after infection there was still a strong negative correlation between TNF-α+IL-2+ CD4 T cells and the level of bacteria (R2 = 0.92 and 0.57, and p<0.0001 and p = 0.0073 for Ag85B and TB10.4, respectively; fig." (PMID 23977248, 2013). "Mice treated with anti-TNFα antibody or lacking TNFα receptor are more vulnerable to infection with mycobacteria." (PMID 24350246, 2013). "Various combinations of IL-6, CRP and TNF-a can maintain sensitivities and negative predictive values above 90% for late-onset infection from presentation until 48 hours afterwards." (PMID 23869218, 2013). "Likewise, bioactive protein and/or mRNA code IL10, IL12p35, TNF-α and INF-α have shown to be up-regulated after infection with APP in vivo or in vitro." (PMID 23698783, 2013). "In contrast, the ω-3 PUFA supplemented group was unable to induce such responses during infection evident by the lack of induction of IFN-γ, TNF-α, IL-17A, IL-22 and IL-23, as well as the chemokine Relm-β compared to pre-infection expression." (PMID 23405155, 2013). "Treatment with mycobacteriophage D29 also resulted in a significant increase of TNF levels in footpads of M. ulcerans infected mice (P<0.01) at day 35 post-treatment (day 68 post-infection), as compared with non-treated mice." (PMID 23638204, 2013). "It was also demonstrated that infection with Rv0805 overexpressing M. tuberculosis elicited lower phosphorylation of CREB and impaired TNF-α production by macrophages, in comparison with wild type bacteria, suggesting a reduced immunomodulatory capacity of this strain." (PMID 23835087, 2013). "We see similar results for the balance of TNF-α and IL-10 in a granuloma at all time points beyond ∼75 days post-infection (data not shown)." (PMID 23869227, 2013). "Subsequently, activated T cells migrate to the site of infection where they release IFN-γ and TNF-α which in turn upregulate inducible nitric oxide synthase (iNOS) in infected macrophages, enabling nitric oxide (NO) mediated killing of the intracellular parasites." (PMID 23437409, 2013). "During infection, SIGNR3 is expressed in lung phagocytes and interacts with Mtb bacilli and mycobacterial surface glycoconjugates and mediates host protection by inducing secretion of protective cytokines including TNFα and IL-6." (PMID 24350246, 2013). "WT and TNF-α−/− mice rapidly cleared C. muridarum by day 6, whereas MHC II−/− mice continued to shed high numbers (>104 IFU) of the organism even on day 9 following reinfection, displaying similar kinetics as in the primary infection." (PMID 23483844, 2013). "RSV infection induces more TLR3 expression and TNFα production than hMPV does, which may partially explain the more severe inflammation observed after RSV infection compared with hMPV infection." (PMID 24039959, 2013). "Given the results of the present study, it seems more likely that the CNS inflammatory response to acute inflammatory events elicited by infection, surgery or trauma, is being driven by TNF-α or IL-1β, rather than IL-6." (PMID 23840908, 2013).
infection (continued). "Upon infection with Nme, a robust inflammatory response marked by elevated chemokines KC, MIP-1α and MIP-2 as well as cytokines TNF-α and IL-1β was observed in the nasal tissue of CEACAM1-humanized mice and also, to a significantly lower extent, in wild-type mice." (PMID 23935487, 2013). "However, mRNA relative expression of IL-8, NF-κB and TNF-α were up-regulated, suggesting that DON could have an effect on the innate immune response which can impair the resistance of chickens to infectious diseases and consequently increase the susceptibility of the host to infection." (PMID 23977054, 2013). "The lung lesions observed in the absence of both IL-1α and IL-1β were similar to those seen in mice deficient for IL-1R1 or TNF, although confluent necrosis was more pronounced in the absence of TNF 4 weeks post-infection." (PMID 25400917, 2013). "Adherence capacity of 21 Colombian isolates, from patients with P. vivax mono-infection to a microvascular line of human lung endothelium (HMVEC-L) was assessed in static conditions and binding was evaluated at basal levels or in tumor necrosis factor (TNF) stimulated cells." (PMID 24080027, 2013). "Higher mRNA expression levels of IL-1β, MCP-1, and TNF-α have been demonstrated in the alveolar macrophages (AMs) of diabetic patients that failed to control infection in contrast to normal AMs." (PMID 24223208, 2013). "Unexpectedly, LCMV Clone 13 infection was not controlled in Il-10fl/flxCD11c-Cre+ mice and resulted in low percentages and total numbers of TNF-α producing antiviral CD8+ and CD4+ T cells comparable to littermate and C57BL/6 controls." (PMID 24244162, 2013). "This defect was only observed during the peak and contraction phase of the response, as lung-resident TNF-/- OT-I cells were indistinguishable from WT OT-I T cells on day 6 post-infection (data not shown)." (PMID 23874808, 2013). "Our data indicate, that bystander apoptosis was mainly induced paracrine, by soluble “death ligands” such as TNF-α, which were synthesized during the infection process,without the necessity of intercellular contact." (PMID 23349721, 2013). "In addition our study reveals elevated TNF and CXCL2 at 24 hours post-infection in Nlrc4−/−/Tlr5−/− mice compared to Nlrc4−/− and WT mice." (PMID 23937571, 2013). "In this study, we evaluated the host responses to C. muridarum in the absence of TNF-α following both primary and secondary intravaginal infection, using TNF-α−/− and the corresponding WT C57BL/6 mice." (PMID 23483844, 2013). "However, upon infection with MAV-1 preincubated with antiserum, secretion of TNF-α from WT cells increased by over 50-fold." (PMID 23596308, 2013). "However, infection with MVA or NYVAC induced the expression of IL-6, TNF-α and IL-10, being this induction higher in KO mice." (PMID 24244156, 2013). "However, previous studies in human and mouse monocytes/macrophages, as well as in mice, have shown that, compared to HN878, infection with CDC1551 induces higher production of inflammatory molecules, including TNF-α and CCL-2." (PMID 23958185, 2013). "Significantly less induction of pro-inflammatory cytokines, TNF-α, IL-6, IL-1β and MCP-1, was found at various time post-infection in ApoE−/− mice; whereas anti-inflammatory cytokine IL-10 was not affected, and IL-12 production was not detectable during infection." (PMID 23977160, 2013). "In the spleens, similar to the JaOArS982 infection, the levels of IFN-γ, IL-2 and IL-4 in IL-10 KO and TNF-α KO mice were significantly increased compared with those of WT mice at 7 days pi following JaTH160 infection, whereas the level of IL-5 was decreased in TNF-α KO." (PMID 23940775, 2013). "VIPhyb-treated BALB/c mice had 2–3 fold more TNF-α expressing CD8+ T-cells than PBS-treated BALB/c mice, while an effect on TNF-α expression was not seen in VIPhyb-treated C57BL/6 mice following mCMV-infection." (PMID 23723978, 2013).
infection (continued). "The low level of TNFα seen with the triple agsΔ mutants fits with the lack of recruitment of neutrophils seen with this mutant after 24 h infection." (PMID 24244155, 2013). "TNF-α is a major pro-inflammatory cytokine produced by mammals during infection with Gram-negative bacteria." (PMID 24489448, 2013). "Both the TB10.4 and ESAT-6 specific immune response in control animals (infection-driven) consisted for comparison primarily of IFN-γ+TNF-α+ CD4 T at both time-points (data not shown)." (PMID 24349004, 2013). "To this end, we found that administration of poly I:C, a TLR3 ligand, to RAG−/− mice throughout the first six weeks of infection, resulted in up-regulation of splenic mRNA for IL-1β, TNF, and CCL2, rather than their down-regulation." (PMID 24130499, 2013). "This study provides the first evidence that TNF-α has an immunoregulatory effect on pro-inflammatory cytokines in the CNS during JEV infection and this results in protection from fatal disease due to infection with this virus." (PMID 23940775, 2013). "In this study, expression levels of IL-4, IL-10, IL-13 and TNF-α were significantly up-regulated while the expression levels of IL-1β,IL-18,IFN-γ, IL-2, IL-15, IL-17F, IFN-α, IFN-β, IL-3 and CSF-1 were markedly decreased in PBMCs at all stages of infection." (PMID 24358317, 2013). "On the other hand, when cPLA2 was blocked 1 h before the infection by treatment of macrophages with cPLA2 antagonist ATK (gray bars), proinflammatory cytokines TNF-α, IL-1β, and IL-6 were upregulated; furthermore, IL-10 expression was significantly affected when cPLA2 was inhibited." (PMID 23555077, 2013). "In the absence of TNFα, accumulation of p-IκBα and IκBα during vA49rev infection was also detected (as observed by conventional immunoblotting), but with the sample sizes tested this was not significant." (PMID 23468625, 2013). "First, we assessed the impact of the absence of TLR2 or TLR9 on the percentage of TNF-α+ cells during the infection." (PMID 23650544, 2013). "Collectively, this data demonstrates that TNFα is required for LN arteriole remodeling during infection, but does not mediate the transient drop in vessel response to NOS inhibition." (PMID 23573281, 2013). "Several cytokines, such as the granulocyte macrophage colony-stimulating factor (GM-CSF), IL-1α, TNF-α, IL-10, IL-17A, IL-2, IL-4 and IL-5, showed a slight but non-significant increase in their serum concentrations upon infection (data not shown)." (PMID 23776551, 2013). "Tracking the gene expression profile of target inflammatory genes, we observed that in WT spinal cords the amount of mRNA for CD3, TNF-α, IFN-γ, iNOS, IL-10 and arginase I increased up between the third and the fifth week after infection, decreasing thereafter." (PMID 23152844, 2012). "We therefore first determined the levels of a panel of markers (IL-1β, IL-6, IL-8, IL-10, IL-12p70, TNF, RANTES, MIG, MCP-1, IP-10, IFN-α, IFN-γ, Ang-1, Ang-2, uPAR and VEGF R1/Flt1) in the plasmas of 79 women who remained infection-free from inclusion through to delivery." (PMID 23155405, 2012). "Infection of BMDC with B. abortus cgs- (cyclic glucan synthase) mutant failed to activate BMDC as measured by the production of TNF-α and IL-12." (PMID 23166489, 2012). "We have also reported that circulating M. bovis BCG-induced TNF is not bioactive but rapidly neutralized by sTNFRs during an infection." (PMID 22666310, 2012). "Neutralizing antibody against anti-mouse TNF-α blocked osteoclast differentiation induced by TNF-α but did not inhibit osteoclast differentiation induced by infection of RANKL-primed BMM with P. gingivalis." (PMID 22723864, 2012). "Furthermore, TNFα induced MMP9 secretion by neutrophils and blocking TNFα in vivo reduced neutrophil recruitment after infection." (PMID 22496659, 2012).
infection (continued). "Using chemiluminescent imaging we measured the concentrations of IL-1a, 1b, 2, 4, 5, 6, 8, 10, 12 (p70), 13, 15, 17 and 23, IFN-γ, TNF-α and TNF-β in duplicate plasma samples available in bio-bank from 9 PI-CFS subjects and 12 recovered controls at 24 months post-infection." (PMID 22973830, 2012). "Lower levels of bradyzoite-containing vacuoles after IFN-γ or IFN-γ/TNF activation of SkMCs as compared to non-activated SkMCs persisted until 144 hours after infection." (PMID 23024821, 2012). "However, it is plausible that by day 16 there was so much infection in C57BL/6 lungs that IL-6 and TNF-α levels increased so that they were more highly expressed in C57BL/6." (PMID 23006927, 2012). "Furthermore, after infection of a MΦ cell line (RAW 264.7 cells) with MCMVdie1 or another ie1-mutant (IE1stop), an approximately 15- to 20-fold higher production of TNFα is also observed in comparison with MCMV." (PMID 22952450, 2012). "Earlier studies have shown that during L. monocytogenes and influenza virus infection, TNF-α/inducible nitric oxide synthase (iNOS)-producing (Tip) DCs failed to accumulate at the site of infection in CCR2−/− mice." (PMID 23272202, 2012). "On another hand, MVA modulates host immune responses after infection of immature human monocyte-derived dendritic cells by increasing IL-12, IFN-β, TNF-α and IL-6 levels, and Toll-like receptor pathways tending to induce specific CD8+ T cell and strong humoral responses." (PMID 22514660, 2012). "Gastric epithelial MKN7 cells produced the pro-inflammatory cytokines IL-6 and IL-8, but not IL-1β, IL-10, IL-12p70 or TNF (data not shown), after infection with H. pylori J99." (PMID 22563496, 2012). "Consistent with this, mice lacking TNFα and IL-1 receptors have reduced inflammatory responses following infection, while macrophages lacking critical counter-regulatory signalling pathways exhibited more severe lung pathology." (PMID 22238612, 2012). "In contrast, unstimulated pMφ secreted similar amounts of TNFα and IL-1βex vivo in pMφ from patients with and without infection." (PMID 22481867, 2012). "Macrophages from CL, ML, SC and HS patients produced low and similar levels of TNF-α at 2 h after infection (data not shown)." (PMID 22458474, 2012). "In contrast, there was no obvious difference in the expression of TNF-α at 16 h, indicating that not all pro-inflammatory cytokine genes are induced at this early stage of infection." (PMID 22438967, 2012). "Infection of monocytes with Udorn also induced the release of IL-6, IL-8, TNFα and IP-10, suggesting that NS1 protein of Udorn does not (effectively) inhibit this host defence response in human monocytes." (PMID 22238612, 2012). "Using real-time PCR, it has been reported that the expression of IFN-γ, tumor necrosis factor alpha (TNF-α), inducible nitric oxide synthase (iNOS), and interleukin (IL)-4 by peripheral blood mononuclear cells (PBMCs) increased in response to infection, whereas that of IL-10 decreased." (PMID 23226242, 2012). "In contrast, TNF-α levels in infected IL-10−/− liver leukocytes were elevated above WT over the course of infection, though these differences were not statistically significant." (PMID 22880122, 2012). "TNF-α expression is not induced early in infection, but its expression is upregulated approximately 30-fold by the day 5 after infection." (PMID 21912565, 2012). "The lack of DC maturation during infection in smooth virulent B. suis is related to the absence of TNF-α secretion." (PMID 22927979, 2012). "In contrast, compared to uninfected control, an infection with S2308 failed to induce significantly changed secretion of TNF-α in WT or Casp2KO BMDCs." (PMID 22927979, 2012). "This suggests that fish TNF-α mainly functions in the recruitment of leukocytes to the site of infection, rather than activating them." (PMID 22811714, 2012).